RECQL (RecQ like helicase)
Diseases named in the same sentence as RECQL in open-access papers (continued):
Sharing a sentence is not in itself a finding about the gene and the disease.
cancer (47 papers, 2007 to 2025). A tumor composed of atypical neoplastic, often pleomorphic cells that invade other tissues. "In 726 IBCs, CD8+, FOXP3+, IL17+, PDL1+, PD1+ T-cell infiltration (TILs) were investigated in RECQL deficient and proficient cancers." (PMID 38134458, 2023). "RECQL loss is therefore expected to increase genomic instability and promote a mutator phenotype leading to increased risk of cancer." (PMID 38134458, 2023). "RECQL is amplified and overexpressed in many clinical cancer specimens, and is associated with cell migration, invasion and metastasis, as well as exhibiting predictive and prognostic biomarker potential." (PMID 32635403, 2020). "Based on the concept that helicases play important roles in the maintenance of chromosomal DNAs, novel therapeutics will be applicable for cancer therapy with siRNAs of the RECQL1 (RECQL) and WRN DNA helicase-encoding genes." (PMID 25729389, 2015). "Moreover, it was found that RECQs exhibited a notable variation in prognosis across different types of cancers, with RECQL, BLM, and RECQL4 showing promising diagnostic potential in LIHC." (PMID 37626815, 2023). "Further case–control studies in large and ethnically diverse populations are needed to better understand whether there is an increased risk of breast or other cancers associated with specific RECQL variants." (PMID 30610487, 2019). "BLM, WRN, RECQL4, and RECQL5 were repressed by stromal and/or immune elements in most types of cancer, while RECQL exhibited reverse patterns." (PMID 37626815, 2023). "KD of RECQL increased the amount of DNA DSBs significantly in three of the six lines, whereas a slight increase was measured for the other three cancer cell lines." (PMID 32820027, 2020). "RECQ1 (also known as RECQL or RECQL1) belongs to the RecQ family of DNA helicases, members of which are linked with rare genetic diseases of cancer predisposition in humans." (PMID 32517021, 2020). "Consistently, we showed that inhibition of RECQL induced DNA DSBs in cancer cells of different origins." (PMID 32820027, 2020). "To test if this effect was dependent on MRE11, we determined the effect of KD of RECQL on DNA DSB formation in the presence of Mirin for two cancer cell lines." (PMID 32820027, 2020). "RECQL is highly expressed in various human cancer types and tumor cell lines, and high expression levels are correlated with poor clinical prognosis." (PMID 32820027, 2020). "RECQL is one of the five RECQ genes, three of which (BLM, WRN and RECQL4) have been implicated in genetic disorders with increased cancer risk." (PMID 30610487, 2019). "BRCA2, BLM, ERCC2, RECQL, REV3L and RIF1 were among the most promising candidates, with some of them previously associated with predisposition syndromes to other cancers." (PMID 30871259, 2019). "Within these genes, AKAP9, CENPE, PRKCI, RDX, RECQL, and USO1 have also been reported to be associated with cancer progression." (PMID 31426369, 2019). "Patients with biallelic gPVs in RECQL4 have been found to develop cancer and other genes that are a part of the RECQL gene family, including RECQL2 (OMIM: 604611) and RECQL3 (OMIM: 604610) have been associated with syndromes predisposing to both malignant and benign neoplasms." (PMID 39979679, 2025). "More recently, mutations in RECQL1 have been identified with the novel genome instability disorder called RECON (RECql ONe) syndrome though cancers have not yet been described in these patients." (PMID 35782872, 2022). "Furthermore, we identified pan-cancer replicated associations of APEX1, RECQL, and DNMT1 with dHRICA (with DNMT1 additionally associating with dHRVAE2)." (PMID 35764656, 2022). "This work shows that RECQL is an essential player in the protection of stalled replication forks and possibly the restart of broken replication forks, thereby representing a target for cancer therapy." (PMID 32820027, 2020). "RECQL is highly expressed in various cancer types and tumor cell lines." (PMID 32820027, 2020).
cancer (continued). "Reduction of RECQL expression resulted in decreased proliferation of different cancer cell lines." (PMID 32820027, 2020). "All together, we showed that the RECQL helicase is an essential player in the protection of stalled replication forks and possibly the restart of broken replication forks, thereby representing a target for cancer therapy." (PMID 32820027, 2020). "This suggests that also in human cancer cells, RECQL prevents MRE11-dependent DNA DSB formation." (PMID 32820027, 2020). "Furthermore, RECQL has been suggested as target for anticancer drugs as its inhibition reduced proliferation of cancer cell lines." (PMID 32820027, 2020). "Therefore, RECQL has been suggested as target for anticancer therapy as inhibition of RECQL reduced proliferation of cancer cell lines." (PMID 32820027, 2020). "To test this hypothesis, we knocked down RECQL using siRNA in different human cancer cell lines and assessed the effect on DNA DSB formation." (PMID 32820027, 2020). "Overexpression of RECQL may provide survival advantage to cancer cells by protecting stalled replication forks against breakage." (PMID 32820027, 2020). "Collectively, our findings identify hitherto unknown non‐enzymatic role of WRN RECQL helicase in pathological mechanisms underlying TOP1cc processing and subsequent NF‐κB‐activation, offering a potential targeted therapy for WRN‐deficient cancer patients." (PMID 35582959, 2022). "Thus, RECQL plays a critical role in sustaining DNA synthesis under conditions of replication stress and as such may represent a target for cancer therapy." (PMID 32820027, 2020). "Because our results suggested that RECQL protects against MRE11-dependent DNA DSB formation, we hypothesized that RECQL is essential in cancer cells suffering from replication stress to prevent replication fork collapse." (PMID 32820027, 2020). "For example, TBPT significantly suppressed a series of genes involved in DNA double-strand break repair, including LIG4, CENPF, DNAJC2, RECQL, SMC6 and BRCA2 (≥ 2-fold), which are also considered vital targets for treating cancer cells without affecting normal cells." (PMID 26986511, 2016).
tumor (25 papers, 2007 to 2024). "T-cell infiltration [CD8+, FOXP3+, and PD1+ cells] and tumor PD-L1 expression was then investigated in RECQL deficient and RECQL proficient IBC." (PMID 38134458, 2023). "Some in vitro functional studies showed that RECQL-deficient tumor cells were more sensitive to DNA-toxic drugs." (PMID 29914420, 2018). "We hypothesized that RECQL deficiency induced genomic instability will not only lead to increased mutagenicity/carcinogenicity but can also increase neoantigen load on tumor cell surface resulting in increased immunogenicity and T-cell infiltration." (PMID 38134458, 2023). "As in the case of tumours deficient in BRCA1/BRCA2, the deficient DNA repair in RECQL-deficient tumours could increase their sensitivity to other drugs blocking compensatory DNA repair mechanisms." (PMID 30610487, 2019). "In the five carriers of RECQL germ-line mutations predicted to abolish its helicase activity, we performed whole genome sequencing (WGS) on matched tumor and germline DNA." (PMID 38134458, 2023). "The expression of LY6D, SCNNA1 and TSPAN1 was higher in tumor tissues than in normal tissues, whereas the expression of RECQL, PEG10 and SEPT3 was lower in tumor tissues than in normal tissues." (PMID 37274269, 2023). "We have previously shown that low levels of RECQL protein is associated with aggressive IBC including larger tumor size, lymph node positivity, high tumor grade, high mitotic index, pleomorphism, dedifferentiation, ER negativity and poor survival." (PMID 38134458, 2023). "Concordantly, inactivation of RECQL in human tumor cell lines of various origins induced DNA DSB formation." (PMID 32820027, 2020). "Therefore, the prognostic significance of LIHC was significantly influenced by factors such as pathological stage, tumor status, and the expression levels of RECQL, WRN, RECQL4, and RECQL5." (PMID 37626815, 2023). "Furthermore, the multivariate analysis in the pure DCIS series with IBC recurrence also demonstrated that low RECQL expression was an independent prognostic factor for tumor recurrence in patients treated with BCS (p = 0.029; HR = 2.913; 95 % CI = 1115–7.608)." (PMID 38134458, 2023). "The cellular mechanism of RECQL effect on the prognosis of ER-positive tumours might be explained by a recent study that explored the role RECQL plays in regulating ERα expression." (PMID 35712517, 2022). "Among these genes, the expression of LY6D, SCNNA1, TSPAN1 and RECQL was significantly higher in tumor tissues than in normal tissues, but the expression of TSPAN1 and RECQL was significantly lower in tumor tissues than in normal tissues." (PMID 37274269, 2023).
RECQL also shares sentences with these, for which no sentence is quoted: glioblastoma (8 papers); genetic disease (7); infection (4); colorectal cancer (3); hepatocellular carcinoma (3); premature aging syndrome (3); triple-negative breast carcinoma (3); brain tumors (2); Breast Invasive Carcinoma (2); cervical carcinoma (2); colon carcinoma (2); hypopharyngeal carcinoma (2); lymph node metastasis (2); oral squamous cell carcinoma (2); osteosarcoma (2); adenocarcinoma (1); anemia (1); B-cell lymphoma (1); bacterial infection (1); benign neoplasm (1); brain glioblastoma (1); brain glioma (1); cataract (1); clear cell adenocarcinoma (1); CNS tumor (1); ductal carcinoma in situ (1); endometrial cancer (1); Fanconi anemia (1); head and neck cancer (1); head and neck squamous cell carcinoma (1).
A further 24 diseases each share a sentence with RECQL in 1 paper.